LEP (leptin)
Diseases named in the same sentence as LEP in open-access papers (continued):
Sharing a sentence is not in itself a finding about the gene and the disease.
prostate carcinoma (continued). "Moreover, leptin promotes the migration and invasion of cells derived from glioma, chondrosarcoma, colon carcinoma, hepatocellular and endometrial carcinoma cells, as well as prostate cancer." (PMID 20030801, 2009). "Despite its limitations, this is the first prospective study examining a potential functional link connecting advanced prostate cancer and CHD, through adiposity and leptin." (PMID 39557398, 2025). "Research in prostate cancer cells demonstrates that leptin, by stimulating the STAT3 signaling pathway, promotes EMT and migration of prostate cancer cells." (PMID 37686525, 2023). "In vitro, treatment with leptin up-regulated HIF-1α and increased adhesion and invasion of prostate cancer cells cultured in oxygen limiting conditions." (PMID 37686525, 2023). "One study suggested a link between fat intake and prostate cancer involving IGF‐1, insulin, or leptin." (PMID 34606688, 2021). "In prostate cancer, an increase in DU145 cell proliferation and invasion and a decrease in cell apoptosis due to ERK1/2 signaling activation after leptin treatment were reported." (PMID 33799880, 2021). "High circulating levels of leptin enhance growth of prostate cancer cells in vitro and PRT has been found to significantly reduce serum leptin levels in obese men." (PMID 32056047, 2020). "Leptin promotes EMT and cell migration by stimulating the STAT3 pathway in DU-145 and PC3 prostate cancer cells." (PMID 33334030, 2020). "The antagonist Lan1 is able to inhibit the phosphorylation of leptin-signalling proteins Jak2, ERK1/2 and Akt, in PC3 and DU145 prostate cancer cell lines." (PMID 28861689, 2017). "The ratio between leptin and adiponectin is imbalanced in obese individuals, leading to abnormalities in the AMPK and mTOR signaling pathways, which may influence prostate cancer development." (PMID 36755926, 2023). "PSMA1, MRAS, LEP, SLC30A3, and RNF7 were found closely related with prostate cancer." (PMID 32528533, 2020). "Some studies show no significantly higher concentration of serum leptin in prostate cancer, compared to healthy patients or patients with benign prostate hyperplasia, or in prostate tumor patients, while others show its concentration to be higher." (PMID 30186533, 2018). "Adipocyte derived leptin promoted the proliferation of androgen-independent human prostate cancer cell lines DU145 and PC-3 rather than androgen-dependent LNCaP-FGC cells, although both cell types expressed functional LepR isoforms." (PMID 30013512, 2018). "Leptin, an hormone activating the same pathway of insulin and IGF-1, stimulate survival of prostate cells hormone independent and increased blood levels of leptin were observed in patients with an aggressive biology of prostate cancer." (PMID 28389628, 2017). "The main goal of this study was to evaluate the effect of preadipocyte and adipocyte secretome in the proliferation, migration and invasion of androgen independent prostate carcinoma cells (RM1) and to assess cell proliferation in the presence of the adiposity signals leptin and insulin." (PMID 25928422, 2015). "Leptin induced the secretion of VEGF, bFGF, TGF-β in prostate cancer cells." (PMID 24202338, 2013). "The overexpression of LEP and ANGPT1 by PP adipose tissue in OB/OW men may contribute towards a favorable environment for prostate cancer progression." (PMID 23009291, 2012). "For instance, they observed that in DU145 prostate cancer cell line, leptin increased the PI3-K pathway by activation of p-Akt in a dose-dependent manner (0–80 ng/mL) at the 4-h time point, whereas in the same cell line, there was a weak p-ERK activity in response to leptin." (PMID 22690216, 2012). "The studies on circulating leptin levels and prostate cancer are not conclusive." (PMID 21566743, 2008).
colon carcinoma (87 papers, 2007 to 2025). "Research has suggested that LEP mRNA expression levels are upregulated in colon cancer tissue and are associated with poor prognosis in patients with colon cancer." (PMID 37282602, 2023). "In fact, increased serum leptin levels have been reported to increase the risk of developing several cancers, including melanoma and colon cancer." (PMID 34745135, 2021). "Serum levels of leptin and expression of its receptor (LPR) are often altered in human colon tumors and leptin has been suggested as a risk factor for colon cancer." (PMID 32380712, 2020). "In several studies, a significant increase in colon cancer risk with higher serum leptin concentration was observed, while others reported significantly lower leptin levels in cancer patients compared to controls." (PMID 28422056, 2017). "Elevated levels of circulating leptin have been shown to increase the risk of colon cancer and other malignancies." (PMID 25019059, 2014). "Significant decrease of tumor cell proliferation was observed in leptin-deficient tumors, and colon tumor growth was dramatically inhibited in leptin-deficient and leptin-receptor-deficient mice." (PMID 23593308, 2013). "Elevated leptin levels have been associated with breast, prostate and colon cancer progression, and leptin promotes in vitro cell proliferation and invasion, as well as independently modulating inflammation." (PMID 23573093, 2013). "Several prospective studies reported that circulating C-peptide and leptin concentrations were more strongly associated with risk of colon cancer than overall colorectal cancer or rectal cancer." (PMID 23072404, 2012). "A similar association of colon cancer and elevated leptin concentrations in males was observed by Stattin and co-workers." (PMID 23173608, 2012). "Serum leptin is a significant risk factor for human colon cancer and leptin enhanced colon tumor cell proliferation in obese mouse models." (PMID 23056418, 2012). "For example, in several studies, a significant increase in colon cancer risk with increasing serum leptin concentrations was reported while others reported significantly lower leptin levels in cancer patients relative to controls." (PMID 21254741, 2010). "An inverse association between colon cancer and circulating sOB-R and leptin was observed." (PMID 37942199, 2023). "Serum leptin and AdipoR1 and AdipoR2 expression levels were found to be associated with lymph node involvement, and AdipoR1 expression was correlated with tumor size in colon cancer patients." (PMID 33167521, 2020). "In clinical, leptin and leptin receptor serves as poor prognostic markers in variant types of cancer including ovarian cancer, colon cancer, AML, gastric cancer, while the prediction of good outcome by the same axis has also been observed in soft tissue cancer." (PMID 29682217, 2018). "However, the causative role of increased leptin in colon cancer is controversial and the data contradictory." (PMID 26347815, 2015). "Moreover, the growth of colon tumors was substantially retarded in leptin-deficient (ob/ob) or leptin receptor-deficient (db/db) mice, suggesting an important role for leptin signaling in tumor regulation in vivo." (PMID 25948792, 2015). "Leptin and adiponectin have been associated with colon cancer and are related to BMI." (PMID 24732966, 2014). "Higher leptin levels are correlated with adiposity and are associated with colon cancer." (PMID 23304125, 2012). "Moreover, we recently could show that incubation of the human NK cell line NK-92 with high levels of leptin led to significantly decreased NKG2D expression accompanied with a significant loss of NK cell cytotoxicity against colon cancer cells." (PMID 28690853, 2017). "Obese mice expressing high levels of LEP showed susceptibility to AOM-induced colon cancer, while colon cancer rats were intervened with LEP, which suppressed colon cancer precancerous lesions." (PMID 40406485, 2025).
colon carcinoma (continued). "Leptin has been demonstrated to promote proliferation, survival, and invasive potential in colon cancer cells by activating MAPK, PI3K, NF-κB, and STAT3 signaling." (PMID 38799159, 2024). "Resistin levels were significantly higher in patients with colon cancer, while serum leptin levels were significantly lower compared with the controls." (PMID 36981858, 2023). "According to Aparicio and colleagues, Leptin is a proliferative factor for different colon cancer cells in vitro nonetheless, hyperleptinaemia in the animal models did not contribute to tumorigenesis." (PMID 37942199, 2023). "In colon cancer, leptin-mediated expression of MMP-7 and cell invasion follow MAPK/ERK and PI3K/AKT signaling pathways." (PMID 37686525, 2023). "Leptin and insulin upregulate miR-4443 in colorectal cancer and decrease the invasiveness of colon cancer cells." (PMID 36964242, 2023). "In colon cancer, leptin exerts pro-carcinogenic effects by the activation of the MAPK (mitogen-activated protein kinase) pathway." (PMID 37185400, 2023). "Another study limitation is that the genetic instruments for lung and colon cancer, as well as adiponectin and leptin were derived from sex-combined data." (PMID 36558416, 2022). "Another mechanism is hypoxia inducible factor (HIF), which correlates with the activation of leptin signalling in many malignancies, including endometrial, pancreatic, breast and colon cancers." (PMID 36556428, 2022). "It was also reported that colon cancer cells exposed to conditioned media from cultured human adipose tissue or exogenous leptin results in a drastic decrease in mitochondrial respiration and expression of mitochondrial proteins." (PMID 33535537, 2021). "High expression of leptin and leptin receptors in colon cancer provides a precondition for the development of colon cancer." (PMID 34485124, 2021). "In colon cancer cells, leptin activates Rho, Rac and cdc42 which are involved in enhancing migration and invasion." (PMID 33582946, 2021). "In colon cancer cells, leptin-induced Akt activation is essential to the anti-apoptotic and proliferative actions." (PMID 33582946, 2021). "To date, many clinical studies on the correlation between leptin and colon cancer have been reported." (PMID 32393372, 2020). "In human colon cancer, upregulation of leptin pathway members was found, and a large network of dysregulated transcripts was linked to poorer overall survival." (PMID 33167521, 2020). "Since, previous reports suggest that leptin is overexpressed in various types of cancer cells and plays a role in the development and progression of a variety of malignancies including colon cancer." (PMID 31742371, 2020). "Although some clinical studies reported the low level of the serum leptin in CRC patients, the high serum leptin level was associated with the high incidence of colon cancer in other studies." (PMID 31231490, 2019). "The concentration of the microflora bacteria, leptin/LPR, and vitamin D/VDR has been associated with colon cancer as environmental factors." (PMID 31231490, 2019). "Results of the present investigations provide first evidence for a leptin-mediated decrease of cytotoxic activity of NK cells when they are coincubated with colon cancer cells." (PMID 28357137, 2017). "Enhancement of prosurvival pathways by leptin has also been shown to counteract the cytotoxic effect of 5-fluorouracil, a common therapeutic agent for colon cancer." (PMID 28915700, 2017). "In vitro investigations demonstrated a decreased IFN-γ secretion and cytotoxicity of human NK cells against colon tumor cells after NK cell preincubation with the adipokine leptin." (PMID 28357137, 2017). "Previous studies showed that leptin reversed sodium butyrate-induced apoptosis in human colon cancer HT-29 cells through MAP kinase and NF-κB pathways." (PMID 27185268, 2016). "The activation of the mentioned pathways by leptin has also been described in endometrial, prostate, liver and colon cancer cells." (PMID 27480179, 2016).
colon carcinoma (continued). "As reported for other epithelial cancers (e.g., colon cancer), leptin stimulates migration and invasion by binding to OB-Rb." (PMID 26053184, 2015). "Leptin shows mitogenic activity in cancers of the colon and has mitogenic and antiapoptotic effects." (PMID 25019059, 2014). "A previous study conducted in our laboratory demonstrated that leptin affects processes related to colon cancer initiation and progression in vitro." (PMID 25019059, 2014). "This discrepancy can be explained by the different experiment settings, using mice tumor epithelial cells vs. human colon cancer cells; and by the different leptin concentrations used." (PMID 24073224, 2013). "The exact molecular signaling pathways mediating this effect are yet to be discovered, however, we have previously found that leptin promotes colon cancer cell metastatic potential by affecting PI3K and Src kinase pathways and activating Rac1 and Cdc42." (PMID 24073224, 2013). "Leptin induced VEGF in mouse colon cells carrying the Apc Min mutation, mutated genotype of adenomatous polyposis coli tumor suppressor gene for colon cancer." (PMID 24202338, 2013). "We conclude that secreted products from the adipose tissue of obese subjects inhibit mitochondrial respiration and function in HCT116 colon cancer cells, an effect that is at least partly mediated by leptin." (PMID 24073224, 2013). "The serum level of leptin is closely related to adipose tissue (AT) mass and was previously found by us to affect colon cancer initiation and progression, in vitro." (PMID 24073224, 2013). "Plasma leptin concentrations in male patients with colon carcinoma tended to be elevated compared to male patients with rectal carcinoma (median leptin: 1.7 ng/ml; range: 0.3 – 19.6 ng/ml vs. 0.9 ng/ml; range: 0.3 – 6.7 ng/ml; p=0.070)." (PMID 23173608, 2012). "In male patients with colon carcinoma, we report elevated leptin concentrations compared to leptin concentrations in rectal tumor patients." (PMID 23173608, 2012). "In metastatic colon cancer cells, leptin provokes the formation of lamellipodia and augments invasion through the MAPK and PI3K pathways." (PMID 22263109, 2012). "In vitro studies have confirmed that leptin promotes cell proliferation, angiogenesis, and metalloproteinase expression in esophageal and colon cancer cell lines." (PMID 23304125, 2012). "In animal models of colon cancer and melanoma, a decline in the expression and secretion of leptin resulted in a reduction of tumor growth." (PMID 22263109, 2012). "Leptin/ObR overexpression in glioma, coupled with recent evidence that the release of leptin from adipose tissue promotes melanoma and colon cancer, provides strong evidence that leptin plays a role in cancer pathogenesis." (PMID 22263109, 2012). "A previous study has reported increased leptin expression in the colons of mice with colon cancer that was secondary to DSS-induced ulcerative colitis." (PMID 22073943, 2011). "C-reactive protein (CRP), albumin, IL-1α, IL-1β, IL-6, IL-8, IL-10, TNF-α, midkine, VEGF-A, VEGF-C, leptin, adiponectin, and ghrelin serum levels are studied in 126 colon cancer patients and 36 healthy subjects." (PMID 20920199, 2010). "Despite these limitations we demonstrated that the levels of resistin and leptin were significantly different between colon cancer patients and controls." (PMID 21254741, 2010). "Resistin levels were significantly higher in colon cancer patients while leptin serum levels were significantly lower as compared to controls." (PMID 21254741, 2010). "Other authors demonstrated that circulating leptin levels in patients with colon cancer were significantly decreased." (PMID 21566743, 2008). "Leptin stimulated proliferation and ameliorated serum-starvation and celecoxib-induced apoptosis in HT-29 colon cancer cells via Akt activation." (PMID 17559672, 2007). "Some studies indicate leptin as a growth factor for colon cancers cell in vitro." (PMID 37942199, 2023).
colon carcinoma (continued). "Chronic increases in LEP concentration may enhance the growth of colonic cancers via the MAPK and PI3-K pathways." (PMID 37282602, 2023). "Leptin influences the expression of some genes which are involved in colon cancer development." (PMID 37942199, 2023). "All of this proves leptin’s modulatory effects in the regulation of colon cancer progression." (PMID 37686525, 2023). "In contrast, other studies claim Leptin is an important factor for colon tumor growth." (PMID 37942199, 2023). "In rat models of colon cancer, CR decreased leptin level and concomitantly reduced tumor growth." (PMID 34205356, 2021). "Interestingly, the unique ability of leptin to target the leptin receptor was exploited to enhance drug delivery in colon cancer." (PMID 33799880, 2021). "In addition, Akt and mTOR inhibitors can downregulate leptin-mediated PI3K/Akt/mTOR signaling which influences the colon cancer cells to proliferate and promote apoptosis." (PMID 32566099, 2020). "LEP binds to mutant LEPR that altered Gln to Arg leads to changes in LEP signaling in the genetic expressions of the key cancer genes and consequently might exposed to the possibility of the breast, lung, oral, and colon cancer." (PMID 33369452, 2020). "Further initial evidence has suggested that probiotics might also be used to actively treat colon cancer due to the involvement of leptin and environmental factors affecting colon cancer carcinogenesis." (PMID 32380712, 2020). "Notably, a recent study in colon cancer pointed out that leptin upregulated miR-4443 to repress TRAF4 and NCOA1 expression leading to the decrease cancer invasion." (PMID 29682217, 2018). "Consequently, it can be assumed that leptin mediates the impaired NK cell activity against colon tumor cells via downregulation of activating NK cell receptors." (PMID 28357137, 2017). "Furthermore, it has been found that leptin acts as a proliferation-stimulating factor in prostate, oesophageal, liver and colon cancer." (PMID 27480179, 2016). "In human colon cancer cells, leptin could also promote proliferation and inhibit apoptosis via activation of JNK mitogen activated protein kinase, JAK2 and PI3 kinase/Akt." (PMID 27185268, 2016). "To assess whether chemokines present in the CM preparations are responsible for the in-vitro effects in colon cancer cell lines, we measured leptin levels in the different CM preparations." (PMID 26472027, 2015). "Leptin stimulated proliferation of human colon cancer cells in vitro and in rat colon and promoted motility and invasiveness of human colon cancer cell lines, but had either potentiating or inhibiting effect on growth of human cancer cells from various other organs in vitro." (PMID 26347815, 2015). "Dysregulation of leptin or its receptors may contribute to colon cancer via effects on growth and proliferation of cancer cells via activation of signaling pathways, including JAK/STAT, PI3-kinase/AKT, and/or MAP kinases." (PMID 26347815, 2015). "Exploring the effect of adipose tissue on cancer progression, we have previously shown that secreted products from the adipose tissue of obese subjects inhibit mitochondrial respiration and function in HCT116 human colon cancer cells, and that the effect is at least partly mediated by leptin." (PMID 26472027, 2015). "In addition, in-vitro assays showed downregulated expression of mitochondrial genes in colon cancer cells exposed to CM prepared from the visceral fat of HFD-fed mice or to leptin." (PMID 26472027, 2015). "Furthermore, both in vivo and in vitro studies demonstrate the ability of leptin to increase colon cancer cell growth." (PMID 24732966, 2014). "A previous study conducted in our laboratory supports the view that leptin may directly affect processes related to colon cancer initiation and progression in colon cancer cells in vitro." (PMID 25019059, 2014).